MIR526A2 (microRNA 526a-2)
Synonyms: hsa-mir-526a-2; MIRN526A-2; MIRN526A2
Gene: MicroRNA gene on chromosome 19 (53,726,922 to 53,726,986, forward strand). Ensembl gene ENSG00000211532.
Gene Ontology:
Biological process: miRNA-mediated post-transcriptional gene silencing